ZBTB16 (zinc finger and BTB domain containing 16)
Description:
Acts as a transcriptional repressor. Transcriptional repression may be mediated through recruitment of histone deacetylases to target promoters. May play a role in myeloid maturation and in the development and/or maintenance of other differentiated tissues. Probable substrate-recognition component of an E3 ubiquitin-protein ligase complex which mediates the ubiquitination and subsequent proteasomal degradation of target proteins.
Synonyms: PLZF; ZNF145
Tractability: PROTAC: ubiquitination databases record sites on it.
Target class: Transcription factor
Gene: Protein-coding gene on chromosome 11 (114,058,335 to 114,256,765, forward strand). Ensembl gene ENSG00000109906.
Subcellular location: Nucleus; Nucleus, nuclear body
Pathways (Reactome):
Immune System: Antigen processing: Ubiquitination & Proteasome degradation
Metabolism of proteins: Neddylation
Gene Ontology:
Molecular function: DNA binding; DNA-binding transcription repressor activity, RNA polymerase II-specific; identical protein binding; protein binding; protein homodimerization activity; RNA polymerase II cis-regulatory region sequence-specific DNA binding; transcription corepressor binding; DNA-binding transcription activator activity, RNA polymerase II-specific; transcription coregulator activity; DNA-binding transcription factor activity; double-stranded DNA binding; protein domain specific binding; type 2 angiotensin receptor binding
Biological process: cartilage development; hemopoiesis; negative regulation of DNA-templated transcription; negative regulation of transcription by RNA polymerase II; positive regulation of cartilage development; positive regulation of chondrocyte differentiation; positive regulation of DNA-templated transcription; positive regulation of fat cell differentiation; positive regulation of ossification; apoptotic process; central nervous system development; mesonephros development; myeloid cell differentiation; negative regulation of myeloid cell differentiation; regulation of transcription by RNA polymerase II; regulatory T cell differentiation; tolerance induction in gut-associated lymphoid tissue; embryonic digit morphogenesis; embryonic hindlimb morphogenesis; ossification involved in bone maturation; positive regulation of multicellular organismal process; positive regulation of NK T cell differentiation; positive regulation of transcription by RNA polymerase II; protein localization to nucleus; protein ubiquitination; and 3 more
Cellular component: nuclear body; nuclear speck; nucleus; PML body; protein-containing complex; transcription repressor complex; chromatin; cytosol
Genetic constraint (gnomAD): Loss-of-function variants: 8 observed, 58.93 expected, observed/expected ratio (o/e) 0.14, 90% interval 0.079 to 0.25. The upper end of that interval is the gene's LOEUF score, 0.25, which puts it in group 1 of 6, group 1 being the genes least tolerant of losing a copy. Missense variants: 625 observed, 949.99 expected, observed/expected ratio (o/e) 0.66, 90% interval 0.62 to 0.7. Synonymous variants: 363 observed, 387.7 expected, observed/expected ratio (o/e) 0.94, 90% interval 0.86 to 1.02.
Cancer hallmarks: cell replicative immortality (promotes or suppresses)
Homologues: Orthologues: chimpanzee ZBTB16 (99% identical), macaque ZBTB16 (99% identical), pig ZBTB16 (98% identical), guinea pig ZBTB16 (97% identical), mouse Zbtb16 (97% identical), rabbit ZBTB16 (96% identical), rat Zbtb16 (96% identical), dog ZBTB16 (96% identical), zebrafish zbtb16a (79% identical), tropical clawed frog zbtb16 (78% identical). Paralogues in human: ZBTB32 (23% identical), PRDM1 (15% identical), PATZ1 (15% identical), ZBTB20 (14% identical), ZBTB18 (14% identical), HIC1 (14% identical), HIC2 (14% identical), ZNF76 (14% identical), ZBTB42 (13% identical), ZNF143 (13% identical), ZBTB7C (13% identical), ZBTB1 (13% identical), and 24 more.
Diseases named in the same sentence as ZBTB16 in open-access papers:
ZBTB16 is named in the same sentence as 167 diseases in open-access papers, as found by Europe PMC text mining. Sharing a sentence is not in itself a finding about the gene and the disease. The quoted sentences say what the papers report.
acute promyelocytic leukemia (58 papers, 2009 to 2025). An aggressive form of acute myeloid leukemia (AML), characterized by arrest of leukocyte differentiation at the promyelocyte stage, due to a specific chromosomal translocation t(15;17) in myeloid cells. "Zinc finger and BTB domain containing 16 (ZBTB16, also known as PLZF), initially discovered as a cause of human retinoic acid-resistant acute promyelocytic leukemia, is a DNA sequence-specific transcriptional repressor." (PMID 34802056, 2021). "A similar phenotype involving the progressive loss of proliferating spermatogonia was reported in Promyelocytic leukaemia zinc finger (Plzf, also known as Zfp145 and Zbtb16)-knockout mice; the expression of this gene is restricted to undifferentiated spermatogonia." (PMID 27649575, 2016). "An example of transcriptional regulation through the interaction with Znf domains of Zbtb proteins is PLZF (Promyelocytic leukemia zinc finger; the same as Zbtb16)." (PMID 39083515, 2024). "Promyelocytic leukemia zinc finger (PLZF) also known as ZBTB16 or ZFP145 was initially found in promyelocytic leukemia as one of the numerous partner proteins attached to the retinoic acid receptor α (RARα) by a reciprocal chromosomal translocation." (PMID 36768269, 2023). "Zinc finger and BTB domain containing 16 (ZBTB16), also named as Zfp145 or promyelocytic leukemia zinc finger, can mediate the binding of Cullin 3 (CUL3) to form CUL3-ZBTB16 complexes." (PMID 35109896, 2022). "A study has reported that ZBTB16 is involved in the development of promyelocytic leukemia through interactions of the BTB-POZ domain with BCL6." (PMID 32517789, 2020). "ZBTB16, also called PLZF, plays an important role in oncogenesis and is first identified in acute promyelocytic leukemia." (PMID 29439675, 2018). "One protein of Kruppel-like zinc-finger proteins family, promyelocytic leukemia zinc-finger protein (PLZF), also known as ZBTB16, was first discovered in acute promyelocytic leukemia as a fusion protein with the retinoic acid receptor α5,6." (PMID 29358655, 2018). "The involvement of ZBTB16 with retinoid receptors is also suggested by the association of a chromosomal translocation to a rare variant of acute promyelocytic leukemia (APL), which fuses the ZBTB16 (PLZF) protein to retinoic acid receptor (RARA)." (PMID 27513748, 2016). "We identified a high frequency of ARID1A mutations, suggesting the involvement of the SWI/SNF chromatin remodeling complexes in the clinical presentation, acute promyelocytic leukemia‐like morphology and all‐trans retinoic acid/arsenic trioxide treatment resistance of ZBTB16‐RARA rearranged AMLs." (PMID 34042280, 2021). "Zinc finger and BTB domain containing 16 (ZBTB16), also known as promyelocytic leukemia zinc finger, was first found in patients with acute promyelocytic leukemia and located on chromosome 11q23 in a gene cluster related to the zinc finger family." (PMID 38789960, 2024). "In acute promyelocytic leukemia (APL), some rare RARA gene rearrangements exhibit resistance to ATRA and arsenic trioxide (ATO), including ZBTB16- RARA and STAT5B- RARA41." (PMID 38902322, 2024). "Zinc finger and BTB domain containing 16 (ZBTB16), also known as promyelocytic leukemia zinc finger, was first found in patients with acute promyelocytic leukemia and is located on chromosome 11q23 in a gene cluster related to the zinc finger family." (PMID 38789960, 2024).
leukemia (30 papers, 2010 to 2025). A malignant (clonal) hematologic disorder, involving hematopoietic stem cells and characterized by the presence of primitive or atypical myeloid or lymphoid cells in the bone marrow and the blood. "ZBTB16 expression has emerged from independent experiments in leukaemia cell lines as a marker of drug resistance." (PMID 41224801, 2025). "All three 11q22.3 deletions involving ATM (sizes: 16, 17, and 18 Mb) also encompassed at least two of the other nearby leukemia-associated genes (BIRC3, ZBTB16, KMT2A, or CBL)." (PMID 36831635, 2023). "ZBTB16 is downregulated in lung cancer, breast cancer, and leukemia, is the first winning TF of the three types of cancer, and, therefore, is a potential general tumor biomarker." (PMID 36101460, 2022). "Here we show that zinc finger and BTB domain containing 16 (ZBTB16)/promyelocytic leukemia zinc finger (PLZF) is a pomalidomide-specific neosubstrate." (PMID 34764413, 2021). "The promyelocytic leukemia zinc finger gene Plzf (also called Zbtb16, Zfp145 or Green's luxoid) belongs to the POZ/zinc-finger family of transcription factors." (PMID 20338044, 2010). "We discover that the zinc-finger and BTB domain-containing protein 16 (ZBTB16), also known as promyelocytic leukemia zinc-finger (PLZF), interacts with ASC in the nucleus to control the conjugation of the Small Ubiquitin-like Modifier (SUMO) to ASC." (PMID 38123560, 2023). "For example, GATA1 partners with HNF1 in hematopoietic progenitor cells; with PPARA:RXRA in leukemia; with SRF, CDX and FOXP3 in primary T-cells; with SRY, NKX2-1, FOXF1, OCT4 and ZBTB16 in differentiated ESCs and with TAL1:TCF3 motif co-occurring in various fibroblasts." (PMID 30142147, 2018).
breast carcinoma (20 papers, 2012 to 2026). "Elevated ZBTB16 expression has been linked to more favorable prognoses in luminal A breast cancers, where it correlates with higher estrogen and progesterone receptor expression." (PMID 41516402, 2026). "In breast cancer, heightened glucocorticoid receptor (GR) activity correlates with improved patient outcomes and is linked to the regulation of the tumor suppressor ZBTB16." (PMID 37902007, 2023). "Other studies initiated in mice revealing host genes that impact metastatic competence in breast cancer include Klf4, Arntl2, and Zbtb16 also have clinical associations." (PMID 35727842, 2022). "In contrast, higher expression of ZBTB16, hsa-miR-130a-3p and hsa-miR-204-5p was significantly associated with better OS in breast cancer." (PMID 33083112, 2020). "Thus, it remains to be determined which innate lymphocyte subset produces the anti-BTLA effect in mice, and which cellular subset mediates the association of ZBTB16 with patient survival in human mammary carcinoma." (PMID 29518903, 2018). "Under normal conditions, ZBTB16 acts as a transcriptional repressor that inhibits breast cancer proliferation and metastasis by upregulating ZBTB28 and antagonizing oncogenic factors such as BCL6/ZBTB27." (PMID 41516402, 2026). "It is reported that Zinc finger and BTB domain containing 16 (ZBTB16) inhibited breast cancer proliferation and metastasis through upregulating ZBTB28 and antagonizing BCL6/ZBTB27." (PMID 38789960, 2024). "The in vitro, in vivo, and clinical data position ZBTB16 as an important hormone‐driven factor that diminishes luminal breast cancer growth and progression." (PMID 37902007, 2023). "In agreement with observations, it is clearly demonstrated that the combination treatment of pyrotinib and chrysin synergistically potentiates autophagy in HER2-positive breast cancer cells via regulating miR-16-5p/ZBTB16/G6PD axis." (PMID 38110365, 2023). "Promoter CpG methylation status causes frequent downregulation of zinc finger and BTB/POZ domain-containing family protein 16 (ZBTB16) in breast cancer cell lines." (PMID 37305392, 2023). "Our validation analysis confirmed that the gain of 5-hmC in TXNL1, BNIPL, CNIH3 and loss of 5-hmC in CHODL, ZBTB16, SP8, and HIC2 in breast cancer samples." (PMID 36230901, 2022). "In breast cancer, ZBTB16 is also downregulated by promoter hypermethylation, and, when activated, it can inhibit breast cancer cells’ proliferation and metastasis." (PMID 36101460, 2022). "In breast cancer, eight winning TFs (ZBTB16, KLF2, KLF4, NR2F1, EGR1, FOSB, EPAS1, and GPRASP1) can form a coregulatory network, and three other winning TFs (MYBL2, FOXM1, and TAL1) can form another coregulatory network." (PMID 36101460, 2022). "Noticeably, PTTG1 gene, the transcriptional promoter of CDK1, was up-regulated in breast cancer; ZBTB16 gene was the transcriptional suppressor of CCNA2, and its expression was down-regulated in overlapping DEGs." (PMID 33083112, 2020). "Our collective preliminary findings supported ZBTB16 is inactivated via promoter hypermethylation in breast cancer." (PMID 32517789, 2020). "Specifically, MDA-MB-231 and BT549 human breast cancer cell lines were stably transfected with pcDNA3.1 or ZBTB16- expressing plasmids and mRNA and protein expression of ZBTB16 were detected via RT-PCR and Western blot, respectively." (PMID 32517789, 2020). "In breast cancer specimens, ZBTB16 expression was significantly downregulated with increased promoter methylation." (PMID 32517789, 2020). "Here, we explored the associations among ZBTB16, BCL6, and ZBTB28 and their relevance in breast cancer." (PMID 32517789, 2020). "ZBTB16 overexpression led to inhibition of proliferation, migration, and invasion of breast cancer cells, reversal of the EMT process, blockage of the cell cycle in G2-M phase, and apoptosis of breast cancer cells in vitro." (PMID 32517789, 2020).
breast carcinoma (continued). "Our experiments clearly demonstrated that ZBTB16 expression was decreased in breast cancer tissues, compared with normal breast and matched paracancerous tissues." (PMID 32517789, 2020). "To reveal functions of ZBTB16 in BrCa (breast cancer), firstly, we examined the effect of ZBTB16 on cell proliferation activity." (PMID 32517789, 2020). "To explore the significance of ZBTB16 in breast cancer, we analyzed the expression of ZBTB16 in 1041 breast tumor and 112 normal breast tissue samples in TCGA along with its promoter methylation status in 735 breast cancer and 92 normal breast tissue samples." (PMID 32517789, 2020). "We observed lower ZBTB16 expression in breast cancer relative to normal tissue samples, which was attributed to gene silencing via methylation of the promoter region." (PMID 32517789, 2020). "Reverse-transcription PCR and methylation-specific PCR were applied to detect expression and methylation of ZBTB16 in breast cancer cell lines and tissues." (PMID 32517789, 2020). "Our data showed that 51.9% of breast cancer tissues were methylated, while no methylation was detected in normal breast tissues, indicating that the promoter methylation of ZBTB16 is a frequent and tumor-specific event in breast cancer." (PMID 32517789, 2020). "MSP analysis disclosed ZBTB16 promoter methylation was present in more than half of the breast cancer cell lines, where ZBTB16 expression was downregulated or depleted." (PMID 32517789, 2020). "ZBTB16 was frequently downregulated in breast cancer cell lines in correlation with its promoter CpG methylation status." (PMID 32517789, 2020). "Based on the data, we proposed that ZBTB16 is a tumor suppressor downregulated in breast cancer, possibly due to abnormal promoter methylation." (PMID 32517789, 2020). "Interestingly, IL1RAPL1 expression correlates with improved prognosis in patients with mammary carcinoma and with the γδ T-cell marker ZBTB16." (PMID 39209451, 2024). "We found that the combination treatment of pyrotinib and chrysin dampened the G6PD expression in HER2-positive breast cancer cells, whereas overexpression of miR-16-5p or knockdown of ZBTB16 increased the G6PD expression in breast cancer cells, along with apparently decreased autophagy." (PMID 38110365, 2023). "The results suggest that the combined treatment of pyrotinib and chrysin synergistically inhibits HER2-positive breast cancer cell survival and proliferation in vitro and in vivo by augmenting autophagy, which is accomplished through the miR-16-5p/ZBTB16/G6PD axis." (PMID 38110365, 2023). "In addition, the expression of ZBTB16 has been shown in other cancers like Breast Cancer to directly induce G2/M phase cell cycle arrest, apoptosis, and inhibition of migration and invasion in these cancer cells." (PMID 37435088, 2023). "In summary, our study identifies for the first time the tremendous therapeutic potential of pyrotinib combined with chrysin in treating HER2-positive breast cancer but also sheds light on the functional role of miR-16-5p/ZBTB16/G6PD axis in the anti-HER2 therapeutic process." (PMID 38110365, 2023). "It was noted that the pyrotinib + chrysin treatment potentiated autophagy in HER2-positive breast cancer cells, whereas the overexpression of miR-16-5p or knockdown of ZBTB16 apparently decreased autophagy, as indicated by simultaneously decreased ratio of LC3-II/LC3-I." (PMID 38110365, 2023). "edu.tw/php/index.php) showed that ZBTB16 was downregulated in 77 paired breast cancer tissues." (PMID 32517789, 2020). "However, the specific associations among ZBTB16, BCL6, and ZBTB28 and their relevance in breast cancer remain to be established." (PMID 32517789, 2020).